THAP10 (THAP domain containing 10)
Tractability: No criterion of Open Targets' tractability assessment is met for any kind of drug.
Gene: Protein-coding gene on chromosome 15 (70,881,342 to 70,892,433, reverse strand). Ensembl gene ENSG00000129028.
Subcellular location (Human Protein Atlas): Nucleoplasm; Cytosol; Golgi apparatus
Gene Ontology:
Molecular function: protein binding; sequence-specific DNA binding
Genetic constraint (gnomAD): Loss-of-function variants: 12 observed, 19.31 expected, observed/expected ratio (o/e) 0.62, 90% interval 0.4 to 1.01. The upper end of that interval is the gene's LOEUF score, 1.01, which puts it in group 4 of 6, group 1 being the genes least tolerant of losing a copy. Missense variants: 310 observed, 339.69 expected, observed/expected ratio (o/e) 0.91, 90% interval 0.83 to 1. Synonymous variants: 127 observed, 134.99 expected, observed/expected ratio (o/e) 0.94, 90% interval 0.81 to 1.09.
Homologues: Orthologues: chimpanzee THAP10 (99% identical), macaque THAP10 (95% identical), dog THAP10 (75% identical), Caenorhabditis elegans mbtr-1 (16% identical), Drosophila melanogaster Sfmbt (16% identical), Caenorhabditis elegans lin-61 (16% identical), Drosophila melanogaster Scm (14% identical), zebrafish phc1 (14% identical), Drosophila melanogaster l(3)mbt (14% identical). Paralogues in human: L3MBTL4 (20% identical), SCML2 (19% identical), L3MBTL3 (18% identical), PHC1 (18% identical), PHC3 (17% identical), SCMH1 (17% identical), SFMBT2 (17% identical), L3MBTL2 (17% identical), MBTD1 (17% identical), L3MBTL1 (16% identical), PHC2 (15% identical), SFMBT1 (15% identical), and 6 more.
Diseases named in the same sentence as THAP10 in open-access papers:
THAP10 is named in the same sentence as 5 diseases in open-access papers, as found by Europe PMC text mining. Sharing a sentence is not in itself a finding about the gene and the disease. The quoted sentences say what the papers report.
breast carcinoma (3 papers, 2017 to 2024). "THAP10, characterized by an N-terminal Thanatos-associated domain with a zinc finger motif similar to DNA-binding domains, shows potential repression in breast cancer and leukemia, but no studies have addressed its function in NB." (PMID 39175876, 2024). "THAP1 has been associated with DYT6 dystonia, THAP5 and THAP1 have been linked to apoptosis, the LRRC49/THAP10 bidirectional gene pair is involved in breast cancer, and THAP11 has been implicated in colon and gastric cancers." (PMID 35893234, 2022). "The LRRC49/THAP10 bidirectional gene pair is reported to have reduced expression in breast cancer." (PMID 35893234, 2022). "THAP10 and LRRC49 (leucine rich repeat containing 49), both located on chromosome 15q23 in close proximity, were simultaneously suppressed due to hypermethylation of the bidirectional promoter region in breast cancer." (PMID 28539478, 2017).
bladder cancer (1 paper, 2025). "Downregulation of THAP10 reduces apoptosis, favoring uncontrolled proliferation, while MELK overexpression is linked to aggressive tumor behavior and poor outcomes in solid cancers, including bladder cancer." (PMID 40867248, 2025).
tumor (4 papers, 2016 to 2025). "Finally, anti‐miR‐383 treatment markedly diminished miR‐383 expression (Fig EV5D), while it increased THAP10 protein levels (Fig EV5D) in tumour tissue." (PMID 28539478, 2017).
THAP10 also shares sentences with these, for which no sentence is quoted: leukaemia (2 papers); gastric cancer (1).